IL1B (interleukin 1 beta)
Diseases named in the same sentence as IL1B in open-access papers (continued):
Sharing a sentence is not in itself a finding about the gene and the disease.
colitis (continued). "Animals with colitis administered with RL-FNPs expressively reduced the expression of TNF-α, IL-1β, IL-6, and IL-12, with effectiveness comparable to that of the dexamethasone group, with the exception of IL-12." (PMID 33499333, 2021). "Ginsenoside Rg1 has been reported to inhibit the release of pro-inflammatory cytokines (IL-1β and TNF-α) by upregulating the expression of NLRP2 and then weaken the inflammatory response of DSS-induced colitis in mice." (PMID 33462754, 2021). "Our results showed the expression levels of pIκB, NFκB p65 (phospho S536), IL-1β, IL-6 and TNF-α were increased in colitis mice." (PMID 34456904, 2021). "In particular, results from previous study showed that apo-bLF was more efficient than the holo form in decreasing MPO, IL-1β, and TNF-α synthesis in trinitrobenzenesulfonic acid (TNBS)-induced colitis in rats and dextran sulfate (DSS)-induced colitis in mice." (PMID 34901112, 2021). "Exposure to IS significantly induced colon shortening, myeloperoxidase activity, IL-1β, IL-6, and TNF-α expression, and NF-κB+/CD11c+ cell population in the colon, resulting in colitis." (PMID 33731795, 2021). "The present study confirmed and extended this effect by detecting a substantial reduction of IL-1α, IL-1β, IL-6, TNF-α, INF-γ, G-CSF, IL-13, GM-CSF, IL-3, MIP-1α, RANTES, and eotaxin cytokines in response to UTA77 treatment in both colitis models." (PMID 34497514, 2021). "In colitis induced by the TNBS model, EA decreased MPO activity, IL-1β concentration, iNOS expression, and MDA concentration but increased IL-10 concentration in intestine tissues." (PMID 35095910, 2021). "Many proinflammatory cytokines, such as IL-6, IL-1β, TNFα, and IL-17, are increased in DSS-induced colitis and UC patients." (PMID 34804049, 2021). "Several pro-inflammatory cytokines, e.g., TNFα, IL-1β, IL-6, and IL-17A, are known to be involved in DSS-induced colitis." (PMID 33871822, 2021). "In experimental colitis, disease severity is often positively correlated with the levels of MPO activity and pro-inflammatory cytokines, such as TNF-α and IL-1β." (PMID 33967768, 2021). "In this study, we determined that arbutin considerably downregulated the levels of inflammatory cytokines (IL-1β, IL-6, and TNF-α) and proteins (iNOS and COX-2) in colitis mice." (PMID 34594215, 2021). "LAG-3 on Tregs was also highlighted in an innate-like cell 3-driven experimental inflammatory model of colitis, where LAG-3+ Tregs specifically targeted CX3CR1+ macrophages, decreasing their production of IL-23 and IL-1β, ameliorating disease." (PMID 34907325, 2021). "Inflammatory response plays a key role in activating the production of mature IL-6, IL-1β, and TNF-α in UC patients and colitis mice." (PMID 34867926, 2021). "Colitis also induced a significant increase in the colonic levels of the pro-inflammatory cytokines TNF-α, IFN-γ, IL-1β, IL-6 and IL-17 measured via CBA." (PMID 34248633, 2021). "LPS treatment increased neuroinflammation and colitis with the induction of TNF-α and IL-1β expression in the colon and hippocampus." (PMID 34579150, 2021). "Our present study has demonstrated that IL-1β-primed ERCs obviously exhibit a more effective immunoregulatory ability and better therapeutic effect in DSS-induced colitis." (PMID 34090510, 2021). "Our results found that BL down-regulated the expressions of IL-1β, IL-6, and TNF-α inflammatory factors in the colon tissue of colitis mice and increased the expression levels of anti-inflammatory factors IL-10 and TGF-β." (PMID 33954162, 2021). "This was accompanied by lower production of colonic inflammatory cytokines (i.e., Nlrp3, IL-1β, IL-6, Tnf-α and Ccl2, REV-ERBα target genes) in colitis mice dosed at ZT10." (PMID 34393786, 2021). "Another flavonoid, myricetin, downregulates inflammatory factors including TNF-α, IL-6, IL-1β, NF-κB, p-NF-κB, PCNA, COX-2, and cyclin D1 in AOM/DSS-induced colitis in mice." (PMID 34950252, 2021).
colitis (continued). "Here, in the present study, we found that IL-1β-primed ERC treatment was also with an enhanced therapeutic effect, through ameliorating colitis symptoms, alleviating the pathological damages, and modulating the balance of immunocytes." (PMID 34090510, 2021). "These include reductions in colitis symptoms, pro-inflammatory markers TNF-α, IL-1β, IL-6, MPO, and PGE2, and levels of NO and MDA, whereas TGF-β expression, GSH levels, and enzyme activities of SOD, CAT, GPx, and GR, were increased." (PMID 34073220, 2021). "Oat β-glucan was shown to prevent DSS-induced colitis by downregulating the levels of TNF-α, IL-1β, IL-6, and iNOS." (PMID 35008842, 2021). "Studies have shown that Astragalus polysaccharide reduces NLRP3 inflammasome activation and IL-1β and IL-18 levels in DSS-induced colitis." (PMID 34462641, 2021). "For example, in dextran sulphate sodium (DSS) colitis, FXR activation via OCA decreases local IL1β and increases systemic IL10 expression." (PMID 34831429, 2021). "We also found high red meat intake induced the production of more inflammatory cytokines such as IL-1β, TNF-α, IL-17, and IL-6 and inflammatory inducible enzymes such as COX-2 and iNOS in dextran sulfate sodium-induced colitis." (PMID 34355008, 2021). "Our studies also showed that AS-IV attenuated the DAI and MPO activity, downregulate the expression of Tnf-α and Il-1β and increase the level of Il-10 and Tgf-β in a dose-dependently manner in DSS-induced colitis mice." (PMID 34589089, 2021). "In another study that used DSS-induced acute colitis model, both LF EA (LEA) and HF EA (HEA) decreased the level of IL-1β, TNF-α, IL-6, and IL-12 in serum." (PMID 35095910, 2021). "TAK-242 treatment during DSS colitis significantly reduced levels of pro-inflammatory and pro-tumorigenic TNF-α and IL-1β in the colon." (PMID 34025672, 2021). "The phenotype named Colitis contains seven DEGs from our lists: IL10, IL11, IL1B, IL1RN, IL6, MIF and TNF." (PMID 34680872, 2021). "The mucosal immune system is activated during colitis, which is accompanied by increasing mRNA expression of pro-inflammatory cytokines, including tumor necrosis factor (TNF)-α, interleukin (IL)-1β, and IL-6." (PMID 34867926, 2021). "Collectively, cinacalcet reduces production of the inflammatory cytokines TNFα, IL-1β, and IL-6 in a DSS-induced colitis model." (PMID 34880751, 2021). "Olaparib reduced the inflammation score, the concentration of IL-1β and IL-6, enhanced the level of IL-10, and decreased the intestinal permeability in TNBS-colitis." (PMID 34567413, 2021). "It was shown that upon CIN-102 treatment, decreased mRNA levels of the pro-inflammatory cytokines IL-1β and TNF-α and increased expression of IL-6 was noted in colonic tissue in mice suffering from colitis." (PMID 34106933, 2021). "Cinacalcet also reduced production of the inflammatory cytokines TNFα, IL-1β, and IL-6 in the colon and sera of mice with DSS-induced colitis." (PMID 34880751, 2021). "The results showed that in mice with colitis, EBN improved symptoms of colitis, reduced colonic injury, and inhibited the increases in the levels of the pro-inflammatory cytokines IL-1β and TNF-α." (PMID 33967768, 2021). "Increased MPO activity and higher levels of pro-inflammatory factors (TNF-α, IL-1β, and INF-γ) in colitis were significantly reversed by naringin." (PMID 34504431, 2021). "The major components and effector molecules of the inflammasome, such as NLRP3, ASC, AIM2, Caspase 1, Caspase 11, IL-18, and IL-1β, play important roles in DSS-induced colitis." (PMID 34721422, 2021). "The mRNA expression levels of pro-inflammatory cytokines, including IL-1B, IL-17, and IL-6, were significantly downregulated in the 3D-TMSC-treated group when compared with those in the colitis control group (P = 0.001, P = 0.001, and P = 0.024, respectively)." (PMID 34599237, 2021).
colitis (continued). "Therefore, the present study was designed to study whether IL-1β pre-stimulation could enhance the therapeutic effects of ERCs on experimental colitis, and try to explain the potential mechanism, which may provide insight into novel strategies to enhance ERC immunoregulatory potency." (PMID 34090510, 2021). "SIRT5 desuccinylates and activates SOD1 to eliminate ROS, desuccinylates and activates PKM2 to block macrophage IL-1β production and prevent DSS-induced colitis, and desuccinylates and activates SHMT2 to drive cancer cell proliferation." (PMID 34930316, 2021). "In this study, clear increases in IL-1β and IL-18 were observed in the colonic mucosae of mice with DSS-induced colitis." (PMID 34462641, 2021). "A hamster mAb anti-IL1β was labeled to 89Zr (89Zr-α-IL1β), and PET imaging was realized to detect inflammation in murine colitis." (PMID 34298967, 2021). "The concentrations of proinflammatory cytokines IL-1β, IL-6, and CCL-2 in the colonic tissues of colitis mice decreased significantly, while anti-inflammatory cytokines IL-33 and IL-10 increased significantly." (PMID 34567209, 2021). "The proinflammatory cytokine levels of IL-1β, TNF-α, IL-6, and IFN-γ were increased whereas the anti-inflammatory cytokine IL-10 was decreased in colitis mice." (PMID 33995942, 2021). "Absence of miR-223 exacerbates inflammation in a murine model of colitis characterized by enhanced NLRP3 inflammasome activation and IL-1β production." (PMID 34026693, 2021). "Mice given 4.5 mg/kg bodyweight of zearalenone for 1 week expressed IL-1β, IL-18, and MPO mRNA transcripts and NLRP3 protein in colonic tissue and exhibited colitis-like symptoms." (PMID 33927703, 2021). "We found that treatment of both L.L-pMU45CR and L.L-pNU45CR reduced IL-6, IL-1β, and TNF-α expression, and restored IL-10 production which plays a regulatory role in colitis." (PMID 34650393, 2021). "In other colitis mouse models, TNF-α, IL-6, and IL-1β in serum and colon were reduced after administering doenjang, fermented soybean paste, and isoflavones such as daidzein and genistein, which are bioactive compounds of soybeans." (PMID 34066160, 2021). "Exposure to EC significantly induced colitis in mice: it induced colon shortening, myeloperoxidase activity, and TNF-α, IL-1β, and IL-6 expression in the colon." (PMID 33731795, 2021). "Otherwise, when treating DSS-induced colitis mice with FCPS, it not only decreased the TLR4 expression but also down-regulated the manufacturing of pro-inflammatory cytokines including IL-1β, TNF-α, and IL-6." (PMID 34199820, 2021). "Cinacalcet significantly reduced both the expression and secretion of TNFα, IL-1β, and IL-6 in the colons of mice with DSS-induced colitis." (PMID 34880751, 2021). "This is accompanied by lower production of colonic inflammatory cytokines (i.e., Nlrp3, IL-1β, IL-6, Tnf-α and Ccl2, all these are REV-ERBα target genes) in ZT10-treated than in ZT2-treated colitis mice." (PMID 34393786, 2021). "Antibiotic-treated mice receiving melatonin-treated feces showed marked relief of Oxa-induced colitis, including weight loss, colonic shortening, and histological severity, which coincided with a decrease in the level of the inflammatory cytokine TNFα, but not in the level of IL-1β, in the colon." (PMID 35116024, 2021). "In this study, we found that the serum levels of TNF-α, IL-1β, IL-6, IL-8, IL-17α, and IFN-γ in colitis mice were significantly decreased by treatment with sinapic acid." (PMID 33312339, 2020). "Andrographolide (Andro), a small molecule, protects mice against colitis-induced colon carcinogenesis by activating mitophagy, suppressing the NLRP3 inflammasome, and reducing IL1B secretion." (PMID 32630319, 2020). "IL-10 signaling is protective against colitis through the regulation of the NLRP3 inflammasome and IL-1β secretion." (PMID 32630319, 2020).
colitis (continued). "TPC immunomodulates by stimulating colon anti-inflammatory cytokines (IL-10) and by downregulating pro-inflammatory cytokines (IL-1β, IL-17, and TNF-α) in collagen-induced arthritis model and DSS-induced colitis model." (PMID 32486445, 2020). "SOCS2−/− mice showed higher disease activity during colitis with increased mRNA expression of the pro-inflammatory cytokines nitric oxide synthase 2 (NOS2) and interleukin 1 β (IL1-β)." (PMID 32349250, 2020). "The levels of IL-1β, IL-6, and TNF-α significantly increased after colitis was induced, and these levels were significantly reduced in the SASP, PCO, TCCO, and OO groups compared with the AA-alone group." (PMID 31936300, 2020). "The mRNA expressions of IL1β and IL6 were dramatically reduced by inhibiting Ninj1 with the blocking peptide during the development of colitis." (PMID 31963519, 2020). "During colitis, TWD increased expression of Tnf by 2.5-fold, Il1b by 2.8-fold, Il4 by 4.8-fold, Il6 by 3.3-fold, Ifng by 3.8, and Il17f by 4.2-fold as compared to mice fed the AIN diet." (PMID 32093192, 2020). "XylB treatments reversed the imbalance between pro- (IL-1β, TNF-α, and IL-17A) and anti-inflammatory (IL-10) cytokines in experimental colitis." (PMID 32429359, 2020). "To assess the protective effect of NZ9000SHD-5 on DSS-induced colitis, we evaluated the protein levels and gene expression of common pro-inflammatory cytokines TNF-α, IL-6, and IL-1β in colon tissue." (PMID 32122364, 2020). "Dextran sulfate sodium (DSS)-induced severe colitis in mice has been suggested to be due to the activation of the NLRP3 inflammasome and release of mature IL-1β." (PMID 33143375, 2020). "Dietary resveratrol treatment ameliorates the increases of secretions of TNF-α and IL-1β and phosphorylation of p65 in DSS-induced colitis mice." (PMID 33664740, 2020). "The mRNA levels of IL-1β, TNF-α, iNOS, IL-6, and iNOS were markedly increased in mice with DSS-induced colitis." (PMID 33536931, 2020). "In a dextran-sulfate-induced colitis animal model, Yue and colleagues showed that the polysaccharides ameliorated the inflammatory response through lowering TNF-α, IL-1β, IL-6, and MPO activity and increased AMPK activity." (PMID 32560291, 2020). "In the present study, we found that vidofludimus inhibited the expression of IL-17 and other inflammatory cytokines including IL-6 and IL-1β, as well as COX-2 in the intestine from DSS-induced colitis mice is dependent on the existence of FXR." (PMID 32477115, 2020). "Synergistically, Rg3-RGE + PT inhibited expression of NO, iNOS, COX-2, IL-1β, IL-6, IL-5, IL-13, and TNF-α in the DSS-induced colitis mice’s macrophage cells, plasma, and colon tissue." (PMID 33182623, 2020). "Administration of B-naphtoflavone, an AhR agonist, improved DSS-induced colitis in mice and downregulated colitis-induced pro-inflammatory cytokines such as TNFα, IL6 and IL1β mRNA." (PMID 32957545, 2020). "gulates NLRP12, inhibits the release of IL-1β and TNF-α, and reduces DSS-induced inflammatory response in colitis in mice." (PMID 32547403, 2020). "The increased secretion of IL-1β, IL-6 and TNF-α has been demonstrated in experimental colitis models and in patients with IBD." (PMID 32971925, 2020). "The administration of HF also inhibited IL-1β production by LPS-stimulated macrophages and ameliorated the severity of DSS-induced colitis." (PMID 33613560, 2020). "Pre-treatment of rats with RES lowered MPO activity, and IL-1β, PGE2 and prostaglandin D2 (PGD2) levels from TNBS-induced colitis." (PMID 32722619, 2020). "Our study found that dietary TS ameliorated neutrophil accumulation in the colon of DSS-induced colitis mice which was accompanied with decreased TNF-α, IL-6, and IL-1β expression." (PMID 33363184, 2020).
colitis (continued). "In contrast, sinapic acid was shown to reduce the generation and mRNA expression levels of some inflammatory cytokines (TNF-α, IL-1β, IL-6, IL-8, IL-17α, and IFN-γ) and reduce the activation of the NLRP3 inflammasome in the colons of colitis mice." (PMID 33312339, 2020). "In TNBS-induced murine colitis, silymarin, has been shown to rebalance inflammatory cytokines such as TNF-α, IL-1β, and IL-6." (PMID 32486445, 2020). "The levels of the proinflammatory cytokines IL1β, IL6 and TNF‐α are increased in both animal models of colitis and patients with UC." (PMID 32363766, 2020). "Soy-derived isoflavones have previously prevented colitis in a murine model and reduced the mRNA levels of TNF-α, IL-1β, IL-6, iNOS, and COX-2." (PMID 32708415, 2020). "The dramatically elevated mRNA expression levels of MCP-1, TNF-α, IL-6, IL-1β, and IFN-γ in the colon are important features of the DSS colitis model." (PMID 33042117, 2020). "Protein levels of mature IL-1β and cleaved caspase-1 were increased in colon tissues of Slco2a1-knockout mice treated with DSS, which led us to hypothesize that NLRP3 inflammasome activation might contribute to the exacerbation of DSS colitis in Slco2a1-deficient mice." (PMID 32184453, 2020). "Inflammation-related factors (Il1b, Tnfa, Il6, Il17, and Inos) were analyzed at the mRNA level in the DSS colitis colon after receiving IFX delivery formulation." (PMID 32933548, 2020). "While obesity alone increases pro-inflammatory IL-1β, TNFα, MCP1, and keratinocyte-derived chemokine, obesity decreased the extent to which TNBS-colitis increased IL-2 and IFN-γ in mesenteric adipose and intestinal tissues." (PMID 33603741, 2020). "It has been noted that the reduction in inflammatory cytokines, such as TNF-α, IL-6, IL-1β, IFN-γ, and IL-17A, in the serum represents a target for IBD therapy, as they play leading roles in the formation of colitis." (PMID 32751784, 2020). "Oral gavage of vancomycin or ampicillin significantly deteriorated tIsc-induced colitis; they dramatically increased colon shortening, myeloperoxidase activity, and TNF-α and IL-1β levels in the colon." (PMID 33324357, 2020). "In this study, the concomitant application of HnAb reduced the intestinal inflammatory damage induced by DSS, assessed by the colitis score, MPO expression and the expression levels of the cytokines IL-1β, IFN-γ, TNF-α in colonic tissues." (PMID 33193406, 2020). "Another study showed that two weeks of RJ administration led to changes in the serum levels of IL-1β, IL-10, and TNF-α in a rat model of colitis." (PMID 33050250, 2020). "First, we found that the colonic mRNA expression levels of the proinflammatory mediators IL-1β, IFN-γ, IL-17A, and TNF-α, which had been confirmed to be involved in IBD, were upregulated notably in colitis mice compared to levels in normal controls." (PMID 32855978, 2020). "Muscadine grapes or wine phytochemicals are capable to decrease MPO activity as well as colonic levels of IL-1β, IL-6, and TNF-α in experimental DSS-colitis." (PMID 32429359, 2020). "According to researchers, flavonoids suppressed the activation of TLR-4/NF-κB p65 signaling pathway, leading to a decrease in gene expression of TNF-α, IL-1B, and IL-6, COX-2, TFF-3, and iNOS proteins in the intestinal mucosa in colitis model." (PMID 32848723, 2020). "BM-MSC exosomes reduced tissue damage, limited myeloperoxidase activity in colon, decreased IL-1β, TNFα and iNOS levels in the tissue in a rat model of 2,4,6-trinitrobenzene sulphonic acid (TNBS)-induced colitis." (PMID 32595362, 2020). "We also observed that sinapic acid treatment significantly reduced the mRNA expression levels of TNF-α, IL-1β, IL-6, IL-8, IL-17α, and IFN-γ in the colons of colitis mice." (PMID 33312339, 2020). "Accordingly, we assume that during the induction phase of colitis, total number of M2 macrophages was higher in colons of Gal-3−/− mice due to the reduced activation of NLRP3/IL-1β pathway." (PMID 31336879, 2019).